PITX1-AS1 (PITX1 antisense RNA 1)
Synonyms: C5orf66
Gene: Long non-coding RNA gene on chromosome 5 (135,033,280 to 135,358,219, forward strand). Ensembl gene ENSG00000224186.
Diseases named in the same sentence as PITX1-AS1 in open-access papers:
PITX1-AS1 is named in the same sentence as 5 diseases in open-access papers, as found by Europe PMC text mining. Sharing a sentence is not in itself a finding about the gene and the disease.
PITX1-AS1 shares sentences with these, for which no sentence is quoted: tumor (3 papers); atherosclerosis (1); cancer (1); malignant melanoma (1); Sepsis (1).